ALB (albumin)
Diseases named in the same sentence as ALB in open-access papers (continued):
Sharing a sentence is not in itself a finding about the gene and the disease.
pneumonia (continued). "A nomogram prediction model based on pneumonia, age, D-dimer, and albumin canhelp clinicians predict the risk of AKI in HF patients with moderatediscriminability." (PMID 39228491, 2024). "The multivariate analysis unveiled several independent risk factors for postoperative pneumonia after craniotomy, including smoking, postoperative albumin, surgical duration, unplanned re-operation, and deep vein catheterization." (PMID 39776439, 2024). "Afterinitial LASSO variable selection, multivariate logistic regression revealed thatage, pneumonia, D-dimer, and albumin were independently associated with AKI inhospitalized HF patients." (PMID 39228491, 2024). "On the other hand, family support and albumin levels were identified as protective factors, suggesting that better family support and higher albumin levels were associated with a lower risk of pneumonia." (PMID 39398953, 2024). "Low preoperative serum albumin levels were significantly associated with postoperative pneumonia and AKI." (PMID 38238681, 2024). "Our research findings are consistent with many previous studies, which demonstrate associations between low preoperative serum albumin levels and increased postoperative pulmonary complications, including pneumonia." (PMID 39496632, 2024). "The present study suggests that serum albumin levels are associated with the occurrence of pneumonia even in subacute stroke patients." (PMID 37762776, 2023). "Univariate logistic regression analysis showed that severe group, WBC count, lymphocyte count, neutrophil count, LDH, CRP, SAA, HS-TnT, albumin, CKMB_M, myoglobin, and sodium were significantly associated with remission of pneumonia (all p < 0.05)." (PMID 37965268, 2023). "In summary, APACHE II score, LIS, SOFA, NUTRIC score, WBC, neutrophils, lymphocyte counts, RAGE, and albumin levels were independent risk factors for severe pneumonia complicated with hypoxemia." (PMID 35035643, 2022). "We found that low serum albumin level on hospital admission was associated to pneumonia, disease severity based on elevation of CRP level and was in fact a clear prognostic factor during one-, two- and five-year surveillance time." (PMID 35189828, 2022). "Studies have pointed out that low serum albumin levels increase the risk of pneumonia, because wounds, fracture healing, and muscle strength recovery require a large amount of protein supplementation." (PMID 35998192, 2022). "Increased age, chronic obstructive pulmonary disease, emergency surgery, postoperative reduced albumin, prolonged ventilation, and longer duration of bed rest were identified as significant risk factors independently associated with postoperative pneumonia." (PMID 35875004, 2022). "Our findings suggest that postoperative albumin levels under 35 g/L in surgical patients is an independent risk factor for postoperative pneumonia." (PMID 35875004, 2022). "Among these factors, the APACHE II score, LIS, SOFA, NUTRIC scores, WBC, neutrophils, lymphocyte count, RAGE and albumin levels were independent risk factors for severe pneumonia." (PMID 35035643, 2022). "Analysis of multiple risk factors confirmed that albumin < 3.5 g/dL and/or urinary bacteria were the only two risk factors associated independently with pneumonia." (PMID 35778707, 2022). "Our study indicated that LAR combining LDH and albumin was associated with the risk of pneumonia in AIS patients." (PMID 34604286, 2021). "Low albumin levels are also a recognized risk factor for developing pneumonia with Pneumocystis jirovecii and as a mortality-associated risk factor in candidemia or fungal peritonitis patients." (PMID 34154403, 2021). "A high RDW/albumin ratio in critically ill patients with pneumonia receiving IMV is associated with 28-day mortality, and there is a similar predictability level for the lactate/albumin ratio, which is a useful combined index of critical illness." (PMID 34943582, 2021).
pneumonia (continued). "The present study showed that high RDW/albumin was associated with increased 28-day mortality in patients with pneumonia." (PMID 34943582, 2021). "As an indicator of nutritional status, serum albumin has been associated with the risk of progressive disease among patients with pneumonia." (PMID 33892752, 2021). "Multiple variables were examined to perform pneumonia risk assessment (i.e., male sex, pressure sores, feeding status and serum albumin level)." (PMID 32059646, 2020). "Based on the multivariate logistic regression model, only eGFR and serum albumin levels remained significantly associated with mortality, indicating the important effect of eGFR on pneumonia patient outcome." (PMID 31071139, 2019). "Pneumonia after surgery in these patients was more common than others (P= 0.023); however, low serum albumin was significantly associated with mortality following operation (P<0.001)." (PMID 25031829, 2014). "Our results agree with the report which showed that low levels of serum albumin associated with greater pneumonia risk in dialysis patients." (PMID 23585903, 2013). "Especially, low albumin and low gamma gap levels were strongly associated for pneumonia death." (PMID 41248155, 2025). "Interestingly, at lower preoperative albumin levels, the risk of pneumonia was more pronounced in younger, female, and generally healthier patients (ASA I-II)." (PMID 41200138, 2025). "Compared with the highest tertile, n albumin level between 38.9 and 45.3 g/L was associated with a 30% increase in risk, and a level <38.9 g/L was associated with a 67% higher risk of postoperative pneumonia." (PMID 41200138, 2025). "This suggests that low albumin levels could serve as a potential biomarker for increased pneumonia risk." (PMID 39857079, 2025). "This benefit may be attributable to several factors associated with higher albumin levels, including a lower incidence of pneumonia and greater relief from hypotension." (PMID 40649163, 2025). "After excluding patients with missing preoperative albumin values (n = 150), those with infectious diseases within 1 month before surgery (n = 220), and those with missing diagnostic data for pneumonia (n = 75), a total of 21,804 patients were included in the final analysis." (PMID 41200138, 2025). "Furthermore, albumin has been shown to independently predict pneumonia risk after acute ischemic stroke." (PMID 39935611, 2025). "On the other hand, low albumin and low gamma gap levels were strongly associated for pneumonia death, and significant interaction was also observed between low albumin and low gamma gap levels for pneumonia death." (PMID 41248155, 2025). "The association between preoperative albumin and postoperative pneumonia." (PMID 41200138, 2025). "Similarly, a high Fg to albumin ratio was reported to be an independent potential risk factor of stroke‐associated pneumonia (SAP)." (PMID 39660934, 2024). "In this study, we identified four independent risk factors that canpredict AKI in hospitalized HF patients: Pneumonia, age, D-dimer, and albumin.Based on these independent risk factors, we developed a nomogram prediction modelto predict the risk of AKI in hospitalized HF patients." (PMID 39228491, 2024). "However, we found that postoperative pneumonia was associated with preoperative serum albumin levels and recurrent nerve palsy." (PMID 38238681, 2024). "Fourth, previous studies have suggested that BUN/ALB ratio was associated with pneumonia." (PMID 36522751, 2022). "HIV, older age, and enrolment at the Malawi site were associated with lower albumin concentrations, while breastfeeding, pre-existing heart disease, and presenting with severe pneumonia or diarrhoea were associated with higher albumin (all p<0.05) in multivariable analysis." (PMID 35398787, 2022).
pneumonia (continued). "The clinical parameters elevated body temperature, heart rate, and respiratory rate, increased lactate dehydrogenase (LDH), aspartate aminotransferase (AST), and C-reactive protein (CRP) levels as well as lower serum albumin level and lymphocyte count were linked with a pneumonia." (PMID 34068311, 2021). "Strong associations were observed across several metabolic pathways: increased plasma concentrations of cholesterol measures, omega-3 and omega-6 fatty acid levels, histidine, branched-chain amino acids and albumin were associated with lower susceptibility to contracting severe pneumonia." (PMID 33942721, 2021). "Therefore, albumin level <3.5 mg/dL is a risk factor for the occurrence and poor prognosis of pneumonia in elderly patients." (PMID 34712677, 2021). "Low albumin levels can lead to poor nutritional reserves and a weak immune system, which may increase the risk of pneumonia." (PMID 34604286, 2021). "For example, lower serum albumin, which was verified as a remarkable risk factor for peritonitis episodes in PD patients, was also demonstrated to be an independent risk factor for pneumonia in our centre’s previous work." (PMID 28583107, 2017). "A retrospective study from China on risk factors for pneumonia in patients with catatonia indicated that prolonged bed rest and smoking significantly increased the risk of pneumonia, whereas better nutritional status, such as higher albumin levels, helped reduce the risk." (PMID 40160203, 2025). "Consequently, elective surgery might be deferred until an optimal preoperative albumin level is attained, thereby mitigating the risk of postoperative pneumonia and other potential complications." (PMID 41200138, 2025). "Furthermore, the decrease in serum ALB levels may increase the risk of venous thromboembolism and pneumonia, thereby affecting functional recovery." (PMID 37731856, 2023). "Moreover, low serum albumin level was associated with pneumonia, dyspnea, over 13-night long stay at ward, death at ward and serum CRP value over 100 mg/L in multivariable logistic regression analysis (P = 0.01, P = 0.02, P = 0.006, P < 0.0001 and P < 0.0001, respectively)." (PMID 35189828, 2022). "Moreover, we found that pneumonia patients with DN were significantly associated with higher BMI and lower serum albumin, which also were independent predictors of pneumonia occurrence even when extensive demographics, comorbidities, and lab adjustments were made." (PMID 23585903, 2013). "The Chinese cohort had higher hemoglobin and albumin levels, and a greater incidence of pneumonia reflecting potential variations in disease phenotype and nutritional status." (PMID 41522506, 2026). "By contrast, lower hemoglobin, albumin, total bilirubin, triglycerides, and likelihood of pneumonia were observed in the MIMIC database." (PMID 41522506, 2026). "Logistic regression identified C-reactive protein and albumin as independent predictors of pneumonia." (PMID 41641131, 2026). "Serum levels of procalcitonin, creatinine, and C-reactive protein were elevated in pneumonia patients, while albumin levels were decreased." (PMID 41641131, 2026). "The primary exposure of interest was preoperative albumin levels, and the outcome was postoperative in-hospital pneumonia." (PMID 41200138, 2025). "In our study, a preoperative albumin level <45.3 g/L was predictive of postoperative pneumonia, which is higher than the threshold reported by Bendersky." (PMID 41200138, 2025). "This study was conducted to evaluate the prognostic value of the neutrophil percentage-to-albumin ratio (NPAR) in pneumonia patients aged 80 years and older admitted to the intensive care unit." (PMID 40364064, 2025). "Patients identified as nutritionally at-risk defined by serum albumin<3.5 g/dL and/or NRS-2002 score ≥3 had significantly higher rates of surgical site infections, anastomotic leaks, pneumonia,delayed gastric emptying, ICU admissions and reoperations." (PMID 41466649, 2025).
pneumonia (continued). "The pneumonia group also had significantly lower albumin levels [3.6 (0.4) g/dL vs. 4.0 (0.4) g/dL], MMSE scores [8.2 (9.4) vs. 18.4 (10.3)], and total lymphocyte counts [1.5 (0.4) × 103/μL vs. 1.7 (0.6) × 103/μL] (p < 0.01)." (PMID 41346384, 2025). "Laboratory findings also indicated that patients with pneumonia had lower lymphocyte (p = 0.04), hemoglobin (p = 0.012), and albumin (p = 0.015) levels and higher LDH levels (p = 0.017)." (PMID 39857079, 2025). "Laboratory findings also revealed decreased hemoglobin, red blood cell count, and albumin levels, a pattern consistent with the findings of Lai LM, who analyzed laboratory data from 16 patients with TW pneumonia." (PMID 40708635, 2025). "Previous studies have demonstrated that some inflammation-nutrition markers, including neutrophil to albumin ratio, neutrophil to lymphocyte ratio, and SIRI, were associated with pneumonia." (PMID 40979209, 2025). "The HRs for any deaths, except pneumonia, with low albumin and high gamma gap levels was higher than those with low albumin and medium gamma gap levels, and the HR was the highest for RSD without pneumonia." (PMID 41248155, 2025). "Among 29 patients with pneumonia, with elevated D-dimer plasma levels (>1 mg/L) and lower albumin serum levels (<3.5 g/dL), 10 patients received seven days of albumin infusions, while the remaining 19 patients served as the control group." (PMID 40699702, 2025). "The pneumonia prediction model, which incorporates factors such as age, smoking history, chest trauma, white blood cell count, serum albumin levels, and GCS, demonstrates high predictive accuracy." (PMID 40708949, 2025). "Previous studies have shown that critically ill patients exhibit significantly higher levels of PCT, CRP, and lactate dehydrogenase (LDH), whereas patients with severe pneumonia have significantly lower albumin levels." (PMID 40247166, 2025). "Ultimately, six factors of age, smoking history, chest trauma, white blood cell count, serum albumin levels, and GCS score were identified as independent risk factors for the development of pneumonia in TBI patients." (PMID 40708949, 2025). "On the contrary, extremely high HR (12.4, 3.98–38.5) was revealed for pneumonia death with low albumin and low gamma gap group." (PMID 41248155, 2025). "This study is the first to demonstrate an independent association between the lactate-to-albumin ratio (LAR) and increased 28-day ICU mortality risk in pediatric patients with severe pneumonia." (PMID 40938884, 2025). "In conclusion, pneumonia, age, D-dimer, and albumin were independent predictorsof AKI in hospitalized HF patients." (PMID 39228491, 2024). "Back to the nature of the CAR, many previous studies had demonstrated the role of CRP and albumin in predicting pneumonia." (PMID 38685951, 2024). "Nevertheless, the findings of our research revealed that individuals diagnosed with pneumonia exhibited reduced levels of albumin." (PMID 38803642, 2024). "Our study revealed that the duration of bed rest, unplanned re-operation, end-tidal CO2, postoperative albumin, and chest X-ray film were significant predictors of postoperative pneumonia." (PMID 39726646, 2024). "Based on the literature, we included the following 10 variables in multivariate logistic regression: age, sex, pneumonia, hemoglobin level, albumin level, ASA grade, type of anesthesia, duration of surgery, Charlson comorbidity index and MFT care." (PMID 38987709, 2024). "In Maiwall’s study, patients with pneumonia and higher lactate levels and SOFA scores were at risk of pulmonary complications after albumin infusion." (PMID 38999366, 2024). "A previous study showed that patients admitted one week after injury had higher incidence of preoperative pneumonia and lower level of albumin." (PMID 36683026, 2023). "Secondary outcomes included the hospital length of stay (LOS), the concentrations of ferritin, C-reactive protein and albumin, oxygen requirements and the severity of pneumonia." (PMID 36986138, 2023).
pneumonia (continued). "There is also a report that the serum albumin level is an independent predictor of nosocomial pneumonia, and that the admission serum albumin level shows a significant negative correlation with the number of infective complications in acute stroke patients." (PMID 37762776, 2023). "Previous studies have also shown that low ALB levels significantly increase pneumonia mortality in kidney transplant recipients." (PMID 37685276, 2023). "The existing literature has demonstrated a correlation between decreased ALB levels and severe pneumonia." (PMID 37685276, 2023). "There were differences in the age, drinking index, and ALB levels between pneumonia and non-pneumonia patients." (PMID 36755225, 2023). "The level of serum albumin was significantly lower with mild pneumonia (36.50 vs. 41.83, P < 0.001)." (PMID 35877031, 2023). "Based on the covariate balancing propensity scores, the two groups were matched using the covariates of age, gender, BMI, the coexistence of pneumonia, albumin level, CRP, and lymphocyte count, and 37 patients were selected from each group." (PMID 37240466, 2023). "Patients who received add-on tigecycline treatment were less likely to receive sulbactam, had higher SOFA scores upon ICU admission, and had lower serum albumin levels on pneumonia index date." (PMID 36597165, 2023). "This prediction model was used as z = 1.815 × tracheal inhibition + 2.012 × artery blood pressure monitoring + 1.650 × fever + 2.087 × antibiotics + 1.750 × pneumonia + (-0.83 × albumin)." (PMID 37714922, 2023). "The present results suggest that the serum albumin level and the FOIS score, which was evaluated as a swallowing-related factor, were associated with the development of pneumonia not only in acute stroke patients, but also in subacute stroke patients." (PMID 37762776, 2023). "BUN/ALB is a novel prognostic marker that has a higher predictive ability than single urea nitrogen and albumin in pneumonia and acute pulmonary embolism." (PMID 36909340, 2023). "Several rodent models of ischemic stroke have demonstrated remarkable efficacy with human serum albumin, it is a potential predictor of pneumonia after an acute ischemic stroke." (PMID 37229192, 2023). "Despite that the patients in both groups had serum albumin within the normal range, albumin levels were significantly lower in patients with mild pneumonia, which is assumed to be the result of proteinuria." (PMID 35877031, 2023). "Plasma fetuin-A levels were negatively correlated with WBC, NE%, Glu, CRP, PCT, CURB-65, and pneumonia severity index scores and positively correlated with albumin level." (PMID 35966877, 2022). "To elaborate, lower RDW, albumin, serum calcium, and blood pH, a higher SOFA score and heart rate, and a higher proportion of pneumonia and respiratory failure were significantly associated with more PerCI according to the analysis of LASSO and SHAP." (PMID 36325351, 2022). "Our in vitro study with chloramine T-induced albumin oxidation provides further insight into the mechanisms of the “cytokine storm” observed in COVID-19-related pneumonia." (PMID 36077496, 2022). "A higher RAR was significantly associated with increased 28-day mortality (odds ratio [OR] 1.338, 95% CI 1.094–1.637, p = 0.005), which is similar to the lactate/albumin ratio in critically-ill patients with pneumonia receiving invasive MV." (PMID 36494633, 2022). "An elevated BUN/ALB level has also been reported as an independent predictor of mortality and pneumonia severity." (PMID 35676675, 2022). "Patients with Adv+ pneumonia showed higher levels of blood glucose [mean [IQR], 6.62 (5.43, 11.05) mmol/L vs. 4.7 (4.22, 5.67) mmol/L, p = 0.001] and lower levels of albumin (p = 0.037) and uric acid (p = 0.008) than did those with Adv+ non-pneumonia." (PMID 36161612, 2022).